SP3 (Sp3 transcription factor)
Diseases named in the same sentence as SP3 in open-access papers (continued):
Sharing a sentence is not in itself a finding about the gene and the disease.
tumor (49 papers, 2008 to 2025). "The positive correlations suggest that higher SP3 expression is associated with increased infiltration of these immune cells into the DLBC tumor microenvironment." (PMID 40128844, 2025). "An investigation into the molecular mechanisms underlying SP3-461aa's tumor-promoting functions, we conducted coimmunoprecipitation experiments in 293T cells overexpressing SP3-461aa-FLAG." (PMID 39440063, 2024). "The expression levels of Sp1 are associated with tumor grade and M stage, and the expression levels of Sp3 were relevant to tumor grade and TNM stage was observed by the clinicopathological characteristics analysis of PC patients." (PMID 35982909, 2022). "The downregulation of CMTM3 in clinical tumor tissues was associated with the methylation of a single CpG site located within the Sp1/Sp3-responsive region of the core promoter." (PMID 24586462, 2014). "Here we tried to decipher the molecular mechanisms implicated in Sp3 accumulation observed in aggressive tumours." (PMID 19212434, 2009). "In a parallel experiment, combined knockdown of Sp1, Sp3 and Sp4 or individual knockdown of Sp1 in L3.6pL cells used in an athymic nude mouse xenograft model showed that loss of Sp TFs resulted in a significant inhibition of tumor growth and tumor weights." (PMID 26967243, 2016). "However, the observed positive association suggests that Sp1 and Sp3 have a similar functional role in the context of the tumor microenvironment although other factors, such as the small sample size, could also contribute to these observations." (PMID 23028678, 2012). "In contrast, CUX1 and ANGPT2 were upregulated in metastatic fibroblasts, and SP3 was upregulated in metastatic tumor cells relative to their expression in the primary tumor." (PMID 40095604, 2025). "Endothelial-specific Sp1/Sp3 knockout reduces angiogenesis in retinal, pathological, and tumor models and induced activation of the Notch1 pathway." (PMID 36759621, 2023). "In this study of tamoxifen-inducible CreERT2-mediated deletion of endothelial Sp1/Sp3 mice, the loss of Sp1/Sp3 delayed the angiogenesis in neonatal retinas, reparative angiogenesis to HLI and skin wound, even the angiogenesis in the subcutaneous tumor." (PMID 36759621, 2023). "Compared with that in adjacent normal tissues, Sp1/Sp3 protein expression levels were also significantly higher in tumor tissues." (PMID 35982909, 2022). "The gene of urokinase receptor (u-PAR) which promotes tumor invasion/metastasis contains Sp1 and Sp3 transcription factor binding sites in the promotor region." (PMID 31075975, 2019). "The failure of fit, both from unity and from the fitted line, is partly due to the localization of Sp3 within the tumor cells." (PMID 26689994, 2016). "Both pro-survival and pro-apoptotic properties have been attributed to Sp3, making it impossible to predict its roles in tumor initiation simply based on perusal of the literature." (PMID 27982060, 2016). "Several reports have referred to a correlation between Sp1 and Sp3 and tumor development, growth and metastasis." (PMID 23326307, 2013). "This demonstrates that, for BA and possibly other drugs that downregulate Sp1, Sp3, Sp4 and Sp-regulated genes, the pathways required for this response are variable and dependent not only on tumor type but also cell context within the same tumor." (PMID 21864401, 2011). "Our results suggest that Enz has a major role in downregulating the u-PAR through Sp1/Sp3 and c-Jun(AP-1), besides HIF1α and VEGFC that are implicated in tumour growth and metastasis, in parallel to upregulating tumour-suppressors relevant for NSCLC." (PMID 20736951, 2010). "The relevance of Sp3 expression for tumour aggressiveness was first evaluated in different tumour cell lines." (PMID 19212434, 2009). "One part of the puzzle has been elucidated since increased Sp3 expression seems progressive from benign to aggressive tumours." (PMID 19212434, 2009).
tumor (continued). "The ambiguous role of transcription factor Sp3 for tumour progression is still debated since it was described as a transcriptional repressor or activator." (PMID 19212434, 2009). "Full length Sp3 accumulation highlights bypass of tumour cell apoptotic capacities and is indicative of head and neck tumours aggressiveness." (PMID 19212434, 2009). "The initiation of tumour development by oncogenes would allow adjustment of Sp3 levels, thus controlling the balance between growth and apoptosis." (PMID 19212434, 2009). "We unsuccessfully tried to constitutively express Sp3 in H&N tumour cells, suggesting that the pro-apototic potential of Sp3 is also efficient in these cells." (PMID 19212434, 2009). "Sp3 over-expression strongly reduces the development of tumours in nude mice confirming its pro-apoptotic potential in vivo." (PMID 19212434, 2009). "The present data have highlighted that accumulation of Sp3 is progressive all along the tumour process." (PMID 19212434, 2009). "For this reason we analysed the relevance of the transcription factor Sp3 as an indicator of tumour aggressiveness." (PMID 19212434, 2009). "Both cells were chosen in order to determine the effect of Sp3 over-expression in a normal and a tumour cell line." (PMID 19212434, 2009). "Different tumour cell lines and head and neck tumour samples were tested for the presence of Sp3 by western blots." (PMID 19212434, 2009). "Both CUX1 and SP3 are key regulators of tumor aggressiveness." (PMID 40095604, 2025). "This relationship implies that SP3 might play a crucial role in modulating immune responses within the tumor, potentially influencing both tumor progression and the effectiveness of immune-based therapies." (PMID 40128844, 2025). "There is also extensive evidence that multiple compounds, including approved drugs that are used for other diseases, induce downregulation or degradation of Sp1, Sp3 and Sp4, which is accompanied by inhibition of cell/tumor growth and invasion and induction of apoptosis." (PMID 36982239, 2023). "Transcription factors Sp1/Sp3 are necessary for fetal development and tumor growth." (PMID 36759621, 2023). "In addition, the expression of these IRGs can be regulated by the transcription factors MYB, SP1, and SP3, which are related to tumor immunity." (PMID 35463955, 2022). "In the Eμ-Myc model, PHIP and SP3 demonstrated clear in vivo tumor suppressor activity." (PMID 27982060, 2016). "Although capture of material from FFPE tumour blocks can be affected by a number of factors (e.g. block age, fixation protocol, cellularity), SP3-CTP consistently demonstrated high-efficiency in protein and peptide recovery from single non-dissected FFPE tissues." (PMID 27713570, 2016). "We previously demonstrated that NEU3 is up-regulated in tumor compared with that in adjacent non-tumor tissues in colon, renal, prostate and ovarian cancers, which may be regulated by Sp1/Sp3 transcriptional factors." (PMID 25803810, 2015). "Sp3 is an inducer of apoptosis and a marker of tumor aggressiveness." (PMID 24993133, 2014). "Tumor lysates from control and treated animals were analyzed by western blot analysis for Sp1, Sp3 and Sp4, and levels were quantitated relative to β-actin and showed significant decreases in expression of Sp1, Sp3 and Sp4 in aspirin vs. control animals." (PMID 23110215, 2012). "The only generalization that could be made was that most amplified cases had a 2+/3+ immunoscore with SP3, and 3+ (any percentage) or 2+ (>50% tumour area) with 4B5 IHC." (PMID 21323962, 2011). "Moreover, betulinic acid, a natural product with anti-tumour activity, induces apoptosis by degrading Sp1 and Sp3." (PMID 19212434, 2009). "Sp3 was more highly expressed in tumour than in normal cell lines (fibroblast, endothelial cells)." (PMID 19212434, 2009). "Our experiments have demonstrated the prognostic role of Sp3 in H&N tumours." (PMID 19212434, 2009).
tumor (continued). "Although it is over-expressed in tumour cells and tumour samples, Sp3 also induces apoptosis." (PMID 19212434, 2009). "Sp3 levels in 52 H&N tumour samples were previously analysed by our team." (PMID 19212434, 2009). "Sp3 induction in established tumours resulted in transient regression then progression." (PMID 19212434, 2009). "We generated normal and tumour cell lines conditionally expressing Sp3." (PMID 19212434, 2009). "Hence, the presence of the full-length active form of Sp3 results in increased transcription of many genes related to tumour growth and angiogenesis." (PMID 19212434, 2009). "In the case of tumour development, Sp3 could first be considered as a tumour suppressor during the initial steps, then as an oncogene, since it boosts growth and angiogenesis." (PMID 19212434, 2009). "Sp3 is over-expressed in tumour cell lines of different origins." (PMID 19212434, 2009). "Consequently, we determined whether endothelial Sp1/Sp3 deletion alters tumor angiogenesis and tumor growth." (PMID 36759621, 2023). "In addition, the western blot data of PC-3-transplanted tumor tissues demonstrated that the protein levels of Sp1, Sp3/4, Survivin, and Cyclin D1 were decreased, while the protein levels of c-Caspase 3 and c-PARP-1 were increased in the HD and PC groups (compared with the NC and LD groups)." (PMID 32851058, 2020). "Of note, we also observed a positive correlation between the tumor vasculature marker CD31 and the protein levels of LRG1, ELK4, SP1 and SP3 in our CRC cohort." (PMID 37786278, 2023). "ELK4 cooperates with SP1 and SP3 instead of SRF to transcriptionally regulate LRG1, among others, to promote tumor angiogenesis, tumor growth, and metastasis." (PMID 37786278, 2023). "Betulinic acid downregulated Sp1, Sp3, Sp4 and EZH2 in tumor tissues and this was accompanied by simultaneous decrease in the levels of miR20a, miR-106a and miR-106b." (PMID 36615262, 2022). "The SENP1 expression level positively correlated with the expression levels of UBN1, SP3, SAP130, NUP98, NUP153 in 32 tumor types." (PMID 34276383, 2021). "It was shown that PDCD4 interacts with Sp1 and Sp3 inhibiting the u-PAR expression and tumor invasion/intravasion." (PMID 31075975, 2019). "This suggest, during SP3 remodeling maintenance phase, ECM proteins may have adverse effects, in-vivo, which may play a role in tumor initiation." (PMID 31040905, 2019). "Both SP3 and PHIP have been reported to exhibit pro-oncogenic activity in some contexts (see Discussion) and yet, in the Eμ-Myc model we clearly identified these as tumor suppressors." (PMID 27982060, 2016). "An alteration in the levels of Sp1 and Sp3 could link MAOB and HiF-1α levels to tumor grade and aggressiveness." (PMID 26689994, 2016). "These functional and quantitative genomic data coupled with the high expression of Sp transcription factors in tumor vs. non-tumor tissue suggests that Sp1, Sp3 and Sp4 are NOA genes and attractive drug targets." (PMID 26967243, 2016). "The analysis of an added E. coli lysate standard for intra-batch normalization revealed only small variations in processing, indicating that the observed expression diversity stems from true biological differences between tumours or histotypes, rather than the SP3-CTP protocol itself." (PMID 27713570, 2016). "Moreover, several studies report that high expression of Sp1 and, in some cases, Sp3 in tumor vs. non-tumor tissue are negative prognostic factors for patients with pancreatic, glioma, colon, gastric, head and neck, prostate, lung and breast cancers." (PMID 26967243, 2016).
tumor (continued). "Thus, the oncogenic-like activity of Sp1, Sp3 and Sp4 and Sp-regulated genes coupled with their overexpression in tumor vs. non-tumor tissue suggests that Sp1, Sp3 and Sp4 are non-oncogene addiction (NOA) genes that are “attractive drug targets”." (PMID 26967243, 2016). "We found no nuclear staining in the tumor samples using SP3 (data not shown), suggesting that rabbit monoclonal antibodies may be less sensitive to detect NuclErbB-2 by IHC than rabbit polyclonal antibodies." (PMID 22356700, 2012).
infection (15 papers, 2008 to 2025). The state of being infected such as from the introduction of a foreign agent such as serum, vaccine, antigenic substance or organism. "To elucidate how the altered binding affinity of SP1/SP3 at the 2SP site specifically enhances NRAMP1 promoter activity after H37Ra infection, we aimed to investigate the roles of SP1 and SP3 in this process." (PMID 40362465, 2025). "Except for the 2SP site, mutations at the 1SP site (−262/−253bp), an adjacent upstream SP1/SP3 recognition site relative to the 2SP site, also showed a specific response to H37Ra infection, but with the opposite effect." (PMID 40362465, 2025). "By substituting the 2SP site with corresponding sequences from humans, pigs, and mice and predicting their respective affinities for SP1/SP3, we observed that a lower affinity of the 2SP site correlates with higher promoter activity following H37Ra infection." (PMID 40362465, 2025). "We identify the V991-specific virulence gene SP3 that is highly expressed during the infection Stage II." (PMID 37968319, 2023). "The specific secretory protein SP3 was identified as a key virulence factor and was highly expressed in the late stage of infection." (PMID 37968319, 2023). "Surprisingly, treatment of PR8-infected mice with Eritoran prior to Sp3 infection reversed this suppression." (PMID 31064834, 2019). "Treatment of mice with Eritoran after PR8 infection and prior to Sp3 infection mitigates lung pathology." (PMID 31064834, 2019). "Sp3 was also detected in the spleen—indicating a translocation and systemic dissemination of the bacteria—from 24 h post-infection onwards." (PMID 31024555, 2019). "During H37Ra infection, SP3 specifically activates NRAMP1 expression by binding to the 1SP site." (PMID 40362465, 2025). "We first detected the expression levels of Sp1 and Sp3 in RAW264.7 cells following H37Ra infection." (PMID 40362465, 2025). "We speculate that only SP3 forms an Mtb-induced complex with other TFs to activate NRAMP1 expression during infection specifically." (PMID 40362465, 2025). "In summary, productive infection was stimulated the most by Sp3, KLF4, GR, and DEX treatment." (PMID 40006984, 2025). "The objectives of this study were to test whether Sp1 or Sp3 cooperate with GR to transactivate the bICP0 E promoter and stimulate productive infection." (PMID 40006984, 2025). "Further, despite containing serotype 3 capsular polysaccharide antigen in their formulae, current vaccines do not effectively prevent infection by Sp3, which often causes severe clinical manifestations in humans." (PMID 38715601, 2024). "Importantly, those that received Eritoran treatment after PR8 infection but prior to Sp3 superinfection showed a significant decrease (P < 0.05) in both COX2 and IFN-β mRNA expression and a nonsignificant trend toward decreased IL-1β and TNF-α mRNA expression." (PMID 31064834, 2019). "At 2 days after Sp3 infection (day 9 postinfection [p.i.]), all mice were euthanized." (PMID 31064834, 2019). "Moreover, protection was observed even when a lethal dose of influenza virus was used to infect mice prior to Sp3 infection." (PMID 31064834, 2019). "However, mice treated with Eritoran on days 2 to 6 after PR8 infection showed significantly enhanced protection from Sp3-induced lethality (from ∼90% to ∼20% lethality; P < 0.0001)." (PMID 31064834, 2019). "We found that the Sp3 strain failed to induce a lethal infection and other signs of disease (weight loss) in naïve mice—even at high doses of challenge (106 or 107 bacteria per animal)." (PMID 31024555, 2019). "Finally, the effect GR and Sp3 have on productive infection was examined." (PMID 40006984, 2025). "In addition, the limited infection of primary microglia observed with both M- and T-tropic viruses can also be attributed to the host-restriction factors expressed in microglia, such as Sp3 protein and C-EBPγ, that function as transcriptional repressors." (PMID 38713307, 2024).
infection (continued). "However, lung sections of PR8-infected, Eritoran-treated mice that were subsequently infected with Sp3 exhibited a significantly diminished lung pathology (bottom right) compared with that of mice infected with PR8 followed by Sp3 infection or mice infected with Sp3 only." (PMID 31064834, 2019). "Therefore, mutations at the 2SP site reduce competition for SP3 binding, enhance the binding efficiency of SP3 at the 1SP site, and thus specifically upregulate NRAMP1 expression during infection." (PMID 40362465, 2025). "It is worth noting that in the non-infected group, SP3 overexpression slightly upregulated Nramp1 expression (1.3-fold), whereas after H37Ra infection, it markedly enhanced the activation of Nramp1 expression (1.9-fold)." (PMID 40362465, 2025). "SP1 demonstrated a greater ability to activate basal transcription, while only SP3, not SP1, specifically enhanced its ability to activate NRAMP1 expression after H37Ra infection." (PMID 40362465, 2025). "We have shown previously that a singular exposure to Sp19F does not confer heterotypic protection against Sp3 rechallenge, in contrast to IAV immunity models in which longer-term infections and antigen presentation can promote extensive lung remodeling after a single IAV infection." (PMID 38715601, 2024).
cardiovascular diseases (3 papers, 2016 to 2023). "The transcription factors Sp1/Sp3 play important roles in various cardiovascular diseases and therefore have been a major research focus." (PMID 36759621, 2023). "From previous studies, we suspected that Sp1 and Sp3 played an important role in the pathogenesis of cardiovascular diseases." (PMID 37735515, 2023). "Sp1/Sp3 represents innovative therapeutic target for captopril to prevent cardiovascular diseases." (PMID 37735515, 2023).
cardiac disease (2 papers, 2021 to 2022). "Taken together, our results suggest that FB_sp2 may serve a crucial role in other cardiac diseases besides MI, and other subpopulations like FB_sp1 and FB_sp3 may also be associated with some specific cardiac diseases." (PMID 35252172, 2022).
head and neck tumours (1 paper, 2009). "The presence of high levels of the full-length form of Sp3 indicates a poor prognosis for overall survival of patients with head and neck tumours." (PMID 19212434, 2009).
kidney diseases (1 paper, 2025). "In the current review article, we mainly highlight the role of SP1 and SP3 in kidney diseases as the other members of SP family protein is less expressed in kidney tissue." (PMID 39850832, 2025). "Targeting SP1 or SP3 may exert positive effects on renal diseases." (PMID 39850832, 2025).
metabolism disorder (1 paper, 2026). "Mechanically, we found that the transcription factor specificity protein 3 (SP3) was activated in HUVECs, responsible for Neu5Ac metabolism disorder." (PMID 42117319, 2026).
SP3 also shares sentences with these, for which no sentence is quoted: bacterial infection (2 papers); cardiac hypertrophy (2); malaria (2); nematode infection (2); thyroid cancer (2); viral infection (2); adenocarcinoma (1); alveolitis (1); Amoebiasis (1); astroglioma (1); bacterial pneumonia (1); cognitive decline (1); Cognitive impairment (1); COVID-19 (1); diphtheria (1); fibrosarcoma (1); gout (1); Huntington disease (1); lung adenocarcinoma (1); melanoma (1); myopia (1); neurodegenerative disease (1); osteoarthritis (1); ovarian serous carcinoma (1); paroxysmal nocturnal haemoglobinuria (1); placental insufficiency (1); prion disease (1); respiratory infections (1); retinal diseases (1); uterine serous carcinoma (1).